INS (insulin)
Diseases named in the same sentence as INS in open-access papers (continued):
Sharing a sentence is not in itself a finding about the gene and the disease.
type 2 diabetes (continued). "This suggests that any dysfunction of brain insulin action due to altered signaling pathway or brain glucose metabolic orders can contribute to hyperglycemia and subsequent glucose intolerance, one of the first manifestations towards the development of Type 2 diabetes." (PMID 22076142, 2011). "Type 2 diabetes mellitus (T2DM) is a complex metabolic disorder characterized by impaired insulin secretion and insulin resistance." (PMID 22163043, 2011). "Thus, RE may be a potent intervention to reverse the compromised insulin-stimulated glucose disposal that is prevalent in Type II diabetes." (PMID 21701685, 2011). "We found that a calorie-restricted vegetarian diet increased insulin sensitivity, reduced volume of visceral fat and improved plasma concentrations of adipokines and oxidative stress markers more than a conventional diet in patients with Type 2 diabetes over 24 weeks." (PMID 21480966, 2011). "In obesity and type 2 diabetes, efficient skeletal muscle repair following injury may be required, not only for restoring muscle structure and function, but also for maintaining exercise capacity and insulin sensitivity." (PMID 21805021, 2011). "However our results and the suggested new role of these molecules in inflammation also suggests that they could be new targets for treatments of type 2 diabetes, as part of their role includes the adaptation of the β-cell to insulin resistance." (PMID 22208362, 2011). "Similarly, thyroid hormone-binding protein transthyretin (Ttr) downregulated by fasting, is increased in insulin-resistant mice, and lowing thyroid hormone-binding protein levels may enhance insulin sensitivity in type 2 diabetes." (PMID 22096593, 2011). "Furthermore, exercise practice in Type 2 diabetes patients showed improved glycemic control, body composition, blood pressure, muscle strength, and workload capacity, together with attenuated progressive increase in exogenous insulin requirements." (PMID 21276212, 2011). "Based on our previous results in type 2 diabetic patients, suggesting that GP treatment exerted a potent anti-hyperglycemic effect by improving hepatic insulin sensitivity, we decided to explore whether GP extract modulates hepatic glucose production in GK rats." (PMID 23675229, 2011). "Since HOMA-B explained only 63% of the association between GLIS3-rs7034200 and type 2 diabetes, additional unknown mechanisms independent of insulin release might also mediate the association." (PMID 21747906, 2011). "Additionally, patients with poorly controlled type 2 diabetes are increasingly being prescribed insulin therapy, with studies suggesting that intensive insulin therapy even in newly diagnosed type 2 diabetes can improve beta-cell survival and function compared with oral hypoglycaemic agents." (PMID 21716654, 2011). "Current ADA/EASD management guidelines in type 2 diabetes suggest that rosiglitazone should be avoided and states that the use of thiazolidinediones in general is less well-validated than the addition of a sulfonylurea or insulin to metformin when antidiabetic combination therapy is required." (PMID 20089006, 2010). "A cohort of 1364 White European individuals at increased risk for type 2 diabetes was characterized by OGTT with glucose, insulin, and C-peptide measurements and genotyped for single nucleotide polymorphisms (SNPs) known to affect glucose- and incretin-stimulated insulin secretion." (PMID 21152029, 2010). "Moreover, insulin use in persons with type 2 diabetes was high." (PMID 20123602, 2010). "This powerful inhibitory effect of pesticides on insulin action likely explains the common finding emerging from several independent cross-sectional studies reporting an association between type 2 diabetes and the body burdens of p,p′-DDE, oxychlordane, or trans-nonachlor." (PMID 20064776, 2010).
type 2 diabetes (continued). "This profile mimics the progressive loss of glucose-stimulated insulin secretion in human type 2 diabetes and, thus, the ZDF rat represents a good animal model for studying human T2DM pathophysiology and the effects of therapeutic options." (PMID 20652060, 2010). "However, their patients with type 2 diabetes were older adults (mean age = 68.59, range = 55 to 81 years) with an average disease duration of 8.29 years, 65.87% of whom were controlled by oral medication and/or insulin." (PMID 20181219, 2010). "Impaired insulin secretion from pancreatic β-cells together with insulin resistance in peripheral tissues represent hallmarks of type 2 diabetes (T2D)." (PMID 19688040, 2009). "Using a computer simulation model of long-term type 2 diabetes progression and based on published data the aim of this analysis was to compare the difference in projected lifetime clinical outcomes for patients immediately initiating versus delaying initiation of insulin." (PMID 19804622, 2009). "Type 2 diabetes (T2D) is characterized by hyperglycaemia that arises via combined defects in insulin secretion (beta-cell dysfunction) and insulin action (in target tissues like adipose tissue, liver and skeletal muscle)." (PMID 19689793, 2009). "Type 2 diabetes (T2D) is characterized by hyperglycaemia and defects in insulin secretion and action at target tissues." (PMID 19689793, 2009). "Interestingly, the Gq/InsP3-coupled 5-HT2CR is a key mediator of the serotonergic suppression of feeding and agonists of this receptor were found to significantly improve glucose tolerance and reduce plasma insulin in murine models of obesity and type 2 diabetes." (PMID 19680544, 2009). "In addition to being used alone or in combination with other oral agents, pioglitazone is also licensed for use in combination with insulin in type 2 diabetes patients with insufficient glycaemic control on insulin, and for whom metformin is inappropriate because of contraindications or intolerance." (PMID 19568428, 2009). "Moreover, they support the idea that an alteration of pancreatic β-cell plasticity, i.e. an inability to recruit fully functional β-cells, could contribute to the impairment of insulin secretion in type 2 diabetes." (PMID 19440374, 2009). "However, the use of any pharmacological therapy for type 2 diabetes, such as thiazolidinedione, insulin, metformin, and other oral hypoglycemic agents or combination therapy with or without insulin appears to be associated with an increased risk of heart failure and body weight gain." (PMID 18523557, 2008). "This 1 : 1 ratio of insulin lispro and ILPS may provide similar HbA1c control and better PPBG control compared with human insulin mix 50 in insulin-requiring patients with type 1 or type 2 diabetes while providing the convenience of injecting immediately before meals." (PMID 18657196, 2008). "Furthermore, it was also assumed that biphasic insulin analogues might have a role in facilitating insulin therapy for type 2 diabetes in the clinical setting, thus contributing to overall improved QOL with insulin therapy." (PMID 18507868, 2008). "The presented data confirm insulin as a normal regulator of oxidative phosphorylation rate in skeletal muscle but as well they could explain cardinal features of the progression of metabolic syndrome and obesity to type 2 diabetes." (PMID 18335029, 2008). "Thus, studies have shown that acute and chronic insulin infusion enhances the transcriptional activity of genes involved in pathways such as energy metabolism in skeletal muscle of healthy subjects and patients with type 2 diabetes." (PMID 18560589, 2008). "On the other hand, decreased expression of UCP-3 in high glucose concentrations may impair beta-cell function, implicating that mechanisms that increase UCP-3 expression and/or function are potential therapeutic targets to offset defects of insulin secretion in humans with type-2 diabetes." (PMID 18167556, 2008).
type 2 diabetes (continued). "Synthetic PPARγagonists are prescribed for their ability to promote insulin sensitivity andlower plasma glucose levels in patients suffering from type 2 diabetes mellitus(T2DM)." (PMID 18288277, 2008). "Since many type 2 diabetic patients exhibit elevated plasma levels of FFA and/or increased glucose levels, the underlying mechanisms for the deleterious action of long-term elevation of FFA on β-cells and glucose-induced insulin release would be highly important to elucidate." (PMID 18478115, 2008). "The increase in insulin secretion reported here (10.8% in TUEF; 8.8% in EUGENE2) within lean rs9402571 G allele carriers was remarkable compared to wild type genotype, and may indicate a protective genotype against type 2 diabetes." (PMID 18985156, 2008). "These in vivo studies may help to explain why patients with type 2 diabetes can show long-term secondary failure to secrete insulin in response to sulfonylureas, but experience restoration of insulin secretion after a drug resting period, without permanent damage to β-cells." (PMID 18959471, 2008). "Initiating insulin in people with type 2 diabetes mellitus (T2DM) is a difficult task and a challenge to the clinician." (PMID 19902044, 2008). "The insulin glargine studies here add to that work, providing validation of the English version (for UK and S.Africa), confirming the validity of the German version for Austria and now Germany for the first time, for patients with both type 1 and type 2 diabetes." (PMID 17927832, 2007). "Finally, patients with type 2 diabetes on split-mixed or premixed twice-daily insulin regimens who are unable to achieve or maintain target A1C goals may also benefit from conversion to basal-prandial insulin regimens." (PMID 17448241, 2007). "Adiponectin exhibits both insulin sensitising, anti-inflammatory and anti-atherogenic properties with serum levels reduced in both type 2 diabetes mellitus (T2DM) and coronary artery disease (CAD)." (PMID 16412224, 2006). "Expression of these genes as well as GSK3 activity is abnormally high in insulin resistant states such as Type 2 diabetes mellitus (T2DM)." (PMID 16600022, 2006). "Thus, it is possible that: a) a mis-regulation of intracellular pH may contribute to the defect in insulin secretion found in type 2 diabetes; and b) Forcing the islet pHi to a lower range may correct/improve this secretory defect." (PMID 16336655, 2005). "Type 2 diabetes mellitus (T2DM) with hyperglycemia (high blood sugar) is a chronic metabolic disorder characterized by persistent high blood glucose levels, often due to insulin resistance and/or inadequate insulin production." (PMID 41481782, 2026). "We carried forwards CpGs identified in EWAS for type 2 diabetes and meta-analysed EWAS for HbA1c and homeostatic model assessment estimates of insulin sensitivity (HOMA-S) as exposures to two-sample MR analysis." (PMID 42032377, 2026). "In type 2 diabetes (T2D) (n = 23) and controls (n = 23), blood SOMAscan proteomic analysis of endothelial proteins at baseline, insulin-induced hypoglycemia and post hypoglycemia to 24 h were examined using repeated-measures linear mixed modeling with a prospective parallel study design." (PMID 41596469, 2026). "In HFD/STZ-induced type 2 diabetic mice, POP intervention significantly reduced hyperglycemia, improved glucose tolerance and insulin sensitivity, and alleviated dyslipidemia." (PMID 41988467, 2026). "5'tRFGlu(CTC) and 5'tRFGly(GCC) are elevated in β-cells and iMACs from db/db mice and in islets from individuals with type 2 diabetes; 5'tRFGlu(CTC) also rises in prediabetes and inversely correlates with insulin secretion." (PMID 42082525, 2026). "Thus, we hypothesized that different phenotypes of patients with Type 2 diabetes can be determined in terms of insulin-mediated glucose uptake patterns in brain regions by using [18F]FDG-PET imaging in combination with a hyperinsulinaemic euglycaemic clamp (HEC)." (PMID 40510539, 2025).
type 2 diabetes (continued). "Hypersecretion of insulin worsens the obese state and, over time, it may lead to failure of beta cells to maintain hypersecretion triggering type 2 diabetes mellitus (T2D) (2-, 4)." (PMID 40561274, 2025). "In our study, the lower MCRI in Black versus White youth with dysglycemia occurred together with higher first‐phase insulin in Black youth, i.e., ~170% in the presence of IGT and ~275% in the presence of type 2 diabetes." (PMID 40470991, 2025). "A key characteristic of the chronic metabolic disease type 2 diabetes, also known as T2D, is impaired insulin responsiveness by the body's cells and dysfunction in the β‐cells of the pancreas; accordingly, blood glucose levels tend to increase and manifest as this illness." (PMID 40918166, 2025). "Compared with type 2 diabetes cases, LADA cases were on average younger, were more likely to be female, had a lower BMI, were more often on insulin treatment, and had lower HOMA-B and HOMA-IR indices." (PMID 39467872, 2025). "A total of 340 insulin‐treated people were included in the study, 156 with type 1 diabetes (35.3% with CSII and 64.7% with ICT) and 184 with type 2 diabetes." (PMID 40818105, 2025). "Interestingly, the antibiotic treatment improved glucose tolerance (by 17%) and insulin sensitivity (by 12%) in Se‐deficient but not Se‐adequate mice, suggesting that dietary Se deficiency reshaped the gut microbiota to a composition favoring type 2 diabetes." (PMID 40540389, 2025). "This expert consensus reviews the reality of primary care clinical management of people with type 2 diabetes (T2D) on non‐intensive insulin therapy, with an emphasis on the use of continuous glucose monitoring (CGM) technology for effective care in this participant group." (PMID 39676327, 2025). "However, given the estimated 5% prevalence of slowly evolving autoimmune type 1 diabetes masking as type 2 diabetes, standardised measurement of autoantibodies may enable insulin-insufficient individuals to be identified, avoiding undue delays in insulin initiation." (PMID 39155282, 2025). "Concurrently, at the metabolic level, PKCθ contributes to the pathogenesis of type 2 diabetes by phosphorylating IRS‐1 in skeletal muscle, thereby disrupting the insulin signaling pathway." (PMID 41244006, 2025). "Type 2 diabetes (T2DM) is a chronic metabolic disorder characterized by insulin resistance (IR) and impaired insulin secretion, leading to hyperglycemia." (PMID 40144137, 2025). "One interesting observation was that their conventional measurements of their insulin-glucose axis (FPG and HbA1c) to diagnose type 2 diabetes were within normal limits under antidiabetic medication before metreleptin administration." (PMID 40415699, 2025). "Type 2 diabetes mellitus (T2DM) is a complex metabolic disorder characterized by chronic hyperglycemia resulting from insulin resistance, impaired insulin secretion, or both." (PMID 41154282, 2025). "Specifically, in type 2 diabetes models, MPC inhibition has been shown to lower blood glucose levels, improve glucose tolerance, and enhance insulin sensitivity." (PMID 40001526, 2025). "Youth with type 2 diabetes versus those with NGT and IGT had higher HbA1c and fasting glucose and lower first‐phase insulin, with a progressive decrease in PIS and DI moving across groups of glucose tolerance from NGT to IGT to type 2 diabetes." (PMID 40470991, 2025). "Sulfonylureas are known to potentiate glucose-induced insulin secretion through the closing of KATP channels and are currently used for the treatment of patients with type 2 diabetes." (PMID 40243540, 2025). "In states of overnutrition and Type 2 Diabetes Mellitus (T2DM)—both significant risk factors for CMVD—sustained mTORC1 activity can induce a negative feedback loop that suppresses insulin signaling, contributing to metabolic dysfunction." (PMID 40948785, 2025).
type 2 diabetes (continued). "Meanwhile, in the context of metabolism, PKCθ impairs the insulin signaling pathway in skeletal muscle by phosphorylating IRS‐1, thereby promoting the development of type 2 diabetes." (PMID 41244006, 2025). "In type 2 diabetes (T2DM), the insulin response is reduced, which is defined as insulin resistance (IR)." (PMID 40809178, 2025). "The excess FFAs are diverted to non-adipose tissues, promoting lipotoxicity and inflammation, which further impair insulin signaling and exacerbate NAFLD and type 2 diabetes." (PMID 40869061, 2025). "The link between obesity and type 2 diabetes (T2DM) is exceptionally strong, since adipose tissue dysfunction impairs insulin signaling, leading to insulin resistance, with the majority of T2DM cases attributable to overweight and obesity." (PMID 40710568, 2025). "Effects of canagliflozin versus placebo on insulin use (initiation, dose intensification, reduction and discontinuation) in people with CKD and type 2 diabetes were evaluated using Cox regression models." (PMID 40036884, 2025). "This systematic review and meta-analysis aim to evaluate the efficacy and safety of tirzepatide in adults with obesity or type 2 diabetes, compared to placebo, GLP-1 receptor agonists (GLP-1 RAs), and insulin." (PMID 40430487, 2025). "In the context of type 2 diabetes, AMPK activation improves insulin sensitivity, enhances glucose uptake in skeletal muscle, and reduces hepatic glucose production, thereby contributing to better glycemic control." (PMID 40563920, 2025). "However, type 2 diabetes requiring insulin therapy could equally benefit." (PMID 41155876, 2025). "Youth with type 2 diabetes versus those with NGT had advanced Tanner stage, lower HDL cholesterol, lower adiponectin, and higher fasting insulin." (PMID 40470991, 2025). "Abnormal values for several glycaemic traits, including fasting glucose (FG), 2 h glucose, fasting insulin (FI), HbA1c, HOMA-B and HOMA-IR, are often observed before clinical diagnosis of type 2 diabetes." (PMID 40025146, 2025). "Patients with type 2 diabetes often have normal or even elevated BMD values, likely influenced by higher body weight and the anabolic effects of insulin on bone tissue." (PMID 40804936, 2025). "Type 2 diabetes mellitus (T2DM) is a complex chronic metabolic disease characterised by hyperglycaemia arising from both insulin resistance and impaired insulin production." (PMID 40430463, 2025). "Given their ability to regulate insulin secretion, GLP‐1, and GLP‐1 analogs were first studied as antidiabetic drugs for type II diabetes." (PMID 39720890, 2025). "Improvements in metabolic health such as improved glucose tolerance and insulin sensitivity and reduced blood pressure, circulating triglycerides, and inflammation may also occur with elevated ketone levels, thereby, improving related conditions such as cardiovascular disease and type 2 diabetes." (PMID 40431405, 2025). "Type 2 diabetes mellitus (T2DM) is a prevalent chronic metabolic disorder, characterised by hyperglycaemia resulting from a combination of insulin resistance and inadequate insulin secretion." (PMID 40566497, 2025). "Type 2 diabetes mellitus (T2DM) is a complex and multifactorial metabolic disorder characterized by chronic hyperglycemia, resulting from impaired insulin secretion and/or insulin resistance." (PMID 40870963, 2025). "Evidence from RCTs suggests that insulin and sulfonylureas increasing insulin secretion has neutral effects on CVD and mortality for adults with type 2 diabetes." (PMID 40003662, 2025). "BPD-DS also rapidly enhances insulin sensitivity—HOMA-IR improves within days postoperatively, and it achieves high rates of type 2 diabetes remission, addressing a key driver of NAFLD." (PMID 40565758, 2025).